AGT (angiotensinogen)
Diseases named in the same sentence as AGT in open-access papers (continued):
Sharing a sentence is not in itself a finding about the gene and the disease.
atherosclerosis (453 papers, 2008 to 2026). A disease characterized by the build-up of fatty material and calcium deposition in the arterial wall resulting in partial or complete occlusion of the arterial lumen. "The expression levels of hs-CRP, TNF-α, NO and EDN1, PTGIS, and AGT genes at risk of atherosclerosis were significantly decreased." (PMID 36180828, 2022). "Genetic deletion of AGT in hepatocytes ablated the development of atherosclerosis in LDL receptor-deficient mice fed a Western diet, demonstrating that hepatocyte-derived AGT contributes to atherosclerosis." (PMID 30530571, 2019). "The fact that the AGT gene constitutes a risk for these disease traits as well as CAD strongly implicates gene-disease interactions in pathways that trigger atherosclerosis, a subject that has attracted considerable research interest recently." (PMID 23497386, 2013). "Our data also provides some support for an association of the AGT polymorphism with the severity of atherosclerosis, independently of other cardiovascular risk traits, possibly strengthening the hypothesis of its involvement in the extent of the disease reported elsewhere." (PMID 23497386, 2013). "Thus, put together, our study identified partly novel associations for various AGT variants concomitantly predisposing individuals to multiple cardiovascular disease traits, pointing to potential pleiotropic activity of the AGT polymorphism on the risk of acquiring atherosclerosis." (PMID 23497386, 2013). "There are many studies linking RAS to CVD development, and it has been demonstrated that the reduction of AGT can reduce atherosclerosis." (PMID 38255276, 2024). "Liver AGT is the major contributor to atherosclerosis and liver supplies AGT to renal proximal tubules." (PMID 37655218, 2023). "Whole-body reduction of AGT, hepatocyte-specific AGT deficiency (hepAGT−/−), and global AGT antisense oligonucleotides (ASO) exerted similar effects on BP and atherosclerosis in LDL receptor−/− mice." (PMID 37293374, 2023). "In conclusion, the BP increase and atherosclerosis development in hypercholesterolemic mice are dependent on AngII generated from hepatic AGT." (PMID 37293374, 2023). "Further, inhibition of megalin, an endocytic receptor for many molecules including AGT and renin on renal proximal tubules, results in profound reductions of renal AngII concentrations and atherosclerosis." (PMID 37655218, 2023). "In contrast to the lack of effect of AGT in leukocytes, whole-body reduction of AGT in an AGT hypomorphic mouse model led to profound decreases in hypercholesterolemia-induced atherosclerosis, supporting that inhibition of AGT protects against atherosclerosis." (PMID 35904033, 2022). "From the vast array of genes that are associated with this condition, AGT, LPL, ITGB2, IRS were identified to play vital role in the pathogenesis of atherosclerosis." (PMID 35241081, 2022). "Suppressing AGT using antisense oligonucleotides has been shown to reduce blood pressure, atherosclerosis, and body weight." (PMID 35586713, 2022). "Collectively, these data from both genetic and pharmacological studies support the beneficial effects of selectively inhibiting liver AGT against atherosclerosis." (PMID 35904033, 2022). "Hepatocyte-specific knockout of AGT in mice resulted in lowered body weight and ameliorated liver steatosis/atherosclerosis after high-fat diet feeding." (PMID 33537089, 2021). "AGT is the substrate to produce AngII, which interacts with its AT1a receptors to promoter atherosclerosis." (PMID 30530571, 2019). "The findings also provide a working basis for the notion of the AGT 3’UTR-trait interactions as an important component of pathways leading to atherosclerosis." (PMID 23497386, 2013).
atherosclerosis (continued). "Adding the causal genes ACE, AGT, AGTR1, and REN to list 2+ (n = 9+4) revealed AOC3 with at least one causal gene to be associated with Transition Metal Ion Binding (GO:0046914, q = 2.288x10-2), and Atherosclerosis (q = 2.821x10-5)." (PMID 39480826, 2024). "Overall, this study unequivocally shows that BP regulation and atherosclerosis in hypercholesterolemic LDL receptor−/− mice are dependent on AngII generated from AGT of hepatic origin, thereby agreeing with the observations made in mice displaying genetic hepatocyte-specific AGT deficiency." (PMID 37293374, 2023). "NF-κB is a significant factor in the pathogenesis of cardiovascular disorders because it regulates multiple genes, including cytokines, binding proteins, ROS, NOS, and angiotensinogen, and other products involved in atherosclerosis, immunological response, inflammation, and proliferation." (PMID 36456799, 2022). "Together with the discovery of several common causative haplotypes for these cardiovascular risk traits and CAD, these findings reaffirm the potential pleiotropic role of the AGT on disease pathways leading to atherosclerosis, possibly involving gene-disease interactive mechanisms." (PMID 23497386, 2013). "The primary question raised in this study was whether or not the interactions of the AGT gene with these risk traits might explain some of the disease pathways to atherosclerosis." (PMID 23497386, 2013). "The different magnitudes of suppressing AGT versus blocking AT1 receptor on BP and atherosclerosis in this study support this notion." (PMID 37293374, 2023). "GalNAc AGT ASO not only reduces BP and atherosclerosis, but also improves diet-induced liver steatosis in mice." (PMID 37293374, 2023). "Compared to losartan, GalNAc AGT ASO led to more profound increases in plasma renin and reduction in BP but had similar effects on atherosclerosis." (PMID 37293374, 2023). "This study demonstrated that GalNAc AGT ASO reduced systolic BP and atherosclerosis in LDL receptor−/− mice fed a Western diet." (PMID 37293374, 2023). "Subsequently, genes related to the atherosclerosis indicators EDN1, PTGIS, AGT, NOS3, ICAM1, and VCAM1 were detected by qPCR." (PMID 36180828, 2022). "For instance, IL-6 stimulates AGT, FBG, CRP, SAA and several complement factors’ synthesis that propagate the downstream inflammatory response responsible for atherosclerosis." (PMID 33407555, 2021). "Accumulating evidence shows that AGT is not only a passive substrate of the RAS, but also plays a critical role in the pathogenesis of obesity and atherosclerosis." (PMID 33537089, 2021). "It induces atherosclerosis locally by inducing inflammation at a plaque site and systemically via the hepatic acute-phase reaction, which involves CRP, angiotensinogen, fibrinogen, and complement components." (PMID 31582904, 2019). "Inducible PTC-specific deletion of AT1aR or ACE or increases of human AGT and renin in adult mice does not affect blood pressure and atherosclerosis in hypercholesterolemic mice." (PMID 37655218, 2023). "Our studies have demonstrated that either whole-body or liver-specific inhibition of AGT synthesis decreases atherosclerosis and reduces renal, but not plasma, AngII concentrations." (PMID 37655218, 2023). "Hepatocyte-specific deletion of AGT reduces renal AGT protein and Ang II production, implicating that liver-derived AGT may contribute to atherosclerosis through augmenting renal Ang II production." (PMID 35904033, 2022). "We can hypothesize that increased levels of AGT in CC individuals may disrupt the delicate balance between the systemic and local RAAS, thus leading to faster atherosclerosis progression and resulting in CAD symptoms occurring at younger ages." (PMID 36360218, 2022). "AGT, ACE, and or AGTR-1 mRNA and protein levels are elevated in arterial cells of type 2 diabetic patients, and RAS inhibition reduces the onset of T2D and prevented atherosclerosis." (PMID 19742300, 2009).
atherosclerosis (continued). "Third, presence of human AGT and renin in PTCs does not augment atherosclerosis in mice." (PMID 37655218, 2023). "Angiotensinogen (AGT) constitutes a central component of the renin-angiotensin system that controls the systemic blood pressure and several other cardiovascular functions and may play an important role in atherosclerosis pathways." (PMID 23497386, 2013).
diabetes (424 papers, 2004 to 2026). "The mechanism(s) by which Nrf2 deficiency leads to the downregulation of renal AGT expression in diabetes remain(s) undefined." (PMID 37760019, 2023). "In this study, we observed a similar association and evaluated the involvement of AGT T174M (rs4762) polymorphism in HTN in the presence of diabetes mellitus, a known risk factor." (PMID 37693342, 2023). "Diabetes alters the way microglia regulate the retinal vasculature, by increasing angiotensinogen expression, causing capillary vasoconstriction and contributing to a loss of vascular reactivity to physiological signals." (PMID 36349522, 2023). "This explains why we observed a strong negative association between prorenin and angiotensinogen and lower angiotensinogen levels following the induction of diabetes in the Ren2 rat." (PMID 36106615, 2023). "Among them, SERPINA1, A2M, and AGT fluctuations are known to be associated with embryogenesis and pregnancy condition and long-term diabetes mellitus." (PMID 33184417, 2020). "The study examined the association of AGT rs4762 with diabetes in a post kidney transplant patients in Korea and found that AGT rs4762 is associated with increased risk of diabetes." (PMID 26682227, 2016). "The aim of this study was to evaluate the association between blood pressure (BP) and urinary angiotensinogen excretion (uAGT) and renal sodium excretion (uNa) in children with type 1 diabetes mellitus (DM1)." (PMID 24880819, 2014). "Use of SNPs Met235Thr in angiotensinogen, T>C (-344) in aldosterone synthase, and G>A (-1903) in chymase genes for prediction of susceptibility to diabetes specific renal disease in the Asian Indian population appears promising." (PMID 16672053, 2006). "Hence, the enrichment of the AGT variants in the type 2 diabetes mellitus group is likely possible due to its association with complications of type 2 diabetes mellitus." (PMID 39561140, 2024). "Also, the risk of diabetes or AGT was higher in those of T1DM mothers than in controls after the data of 2–5 year olds and 20 year olds were synthesized, while T1DM mothers generally do not have strong genetic background of T2DM." (PMID 29329330, 2018). "To date, there is only one report on the association between AGT rs4762 and diabetes." (PMID 26682227, 2016). "Small interfering RNA (siRNA) therapy targeting hepatic angiotensinogen (AGT) has demonstrated significant renal protective effects in animal models of diabetes." (PMID 41226756, 2025). "We observed reduced methylation in the angiotensinogen metabolism pathway in patients with diabetes." (PMID 38967555, 2024). "Plasma angiotensinogen prior to diabetes induction amounted to 706 ± 32 pmol·ml−1 and plasma renin and prorenin were 41 ± 2 and 507 ± 33 ng angiotensin I per ml·h−1, respectively (n = 47 for all)." (PMID 36106615, 2023). "In contrast to male rodent models of obesity and diabetes, females are protected from metabolic and cardiovascular derangements produced by angiotensinogen, renin, and angiotensin II." (PMID 37049573, 2023). "There is evidence that metabolic complications, such as diabetes and obesity, are associated with the upregulation of RAS components such as angiotensinogen, ACE, and AT1R." (PMID 37106756, 2023). "In the jejunum, diabetes decreased the expression of the Mas receptors and angiotensinogen mRNA levels." (PMID 35682739, 2022). "Although angiotensinogen is predominantly expressed in the proximal tubule, several studies have shown that the glomerular angiotensinogen levels are increased under pathophysiologic conditions, including diabetes." (PMID 34790127, 2021). "Angiotensinogen metabolites are involved in vascular complications of diabetes, such as myocardial infarction, stroke, nephropathy, retinopathy, and foot ulcers." (PMID 27803936, 2016).
diabetes (continued). "We found that AGT mRNA was increased in the heart in diabetes almost twofold and this effect was reversed by miR-133a overexpression, suggesting that miR-133a inhibits activation of the local renin–angiotensin system." (PMID 24428157, 2014). "Furthermore, catalase overexpression attenuated intrarenal AGT expression in an animal model of diabetes." (PMID 40362266, 2025). "At 15 weeks of diabetes, immediately prior to the treatment period, plasma renin was unchanged, prorenin had quadrupled to 1948 ± 179 ng angiotensin I per ml·h−1, and plasma angiotensinogen was reduced to 322 ± 22 pmol·ml−1." (PMID 36106615, 2023). "Additionally, microglia at this time (4 weeks of diabetes) were found to exhibit increased expression of angiotensinogen while retinal fractalkine levels were increased in rat retinae 4 weeks following the onset of diabetes." (PMID 36349522, 2023). "Indeed, some studies have found that SGLT2 inhibitors lower renal tissue AGT expression, whereas others have shown the opposite using the same diabetes mouse model." (PMID 35710133, 2022). "And functional polymorphisms in the ACE, AGT, and AGTR1 can impact the expression or the function of encoded proteins, and are related to stroke, coronary heart disease, vascular dysfunction and diabetes." (PMID 34150864, 2021). "Evidence has suggested that AGT levels are increased in the intrarenal renin-angiotensin system in diabetes, and the enhanced intrarenal AGT levels may contribute to the progression of diabetic nephropathy." (PMID 32566679, 2020). "Previous literature has predominantly focused on the vasoconstrictor arm of the RAS and shown that, in contrast to male rodent models of obesity and diabetes, females are protected from metabolic and cardiovascular derangements produced by angiotensinogen, renin, and angiotensin II." (PMID 31262355, 2019). "Similarly, urinary angiotensinogen and sodium excretions are significantly increased in normo-albuminuric children with diabetes." (PMID 29600408, 2018). "Elevation of urinary AGT has also been confirmed to be related to not only development but also progression of DN based on studies in patients with DN, as well as mouse and rat models of diabetes." (PMID 29053707, 2017). "However, AGT was also expressed in glomerular cells, particularly in the mesangial cells under pathological conditions, such as diabetes." (PMID 27801805, 2016). "As for AGT rs5051, to the best of our knowledge, there is no published report on the association with diabetes, and our study provides a novel report." (PMID 26682227, 2016). "This study focused on the effects of a DPP-4 inhibitor on urinary AGT in patients with diabetes." (PMID 26380312, 2015). "Even though ARB may affect AGT synthesis and urinary AGT, the effects of ARB on urinary AGT in patients with diabetes are beyond the scope of this study, and we need another study to address this issue." (PMID 26380312, 2015). "The augmented intrarenal AGT mRNA expression parallels renal dysfunction in patients with diabetes." (PMID 24284398, 2013). "Therefore, this study was performed to demonstrate increased RAS-related factors (especially AGT mRNA/protein) in proximal tubules of patients with diabetes." (PMID 24284398, 2013). "However, clear evidence that RAS-related factors (especially AGT mRNA/protein) in the proximal tubules are increased in patients with diabetes is very scarce." (PMID 24284398, 2013). "Moreover, the augmented intrarenal AGT mRNA expression paralleled renal dysfunction in patients with diabetes." (PMID 24284398, 2013). "Indeed, urinary AGT levels (uAGT) can be used as an indicator of RAS activation in diabetes." (PMID 38203807, 2024). "However, another study of patients with non-diabetic kidney disease with substantial proteinuria reported that the percent change in urinary AGT, not baseline urinary AGT, was associated with the percentage change in proteinuria during losartan treatment." (PMID 32410703, 2020).
diabetes (continued). "Thus, it can be speculated that during the development of diabetes, high glucose initially increases intrarenal angiotensinogen levels, leading to generation of Ang II in the kidney." (PMID 29600408, 2018). "However, an increase in urinary AGT appears earlier than an increase in urinary Alb in diabetes." (PMID 26380312, 2015). "SGLT-2 inhibitors were found to induce a modest increase in plasma levels of aldosterone and AngII, but still within the low range typical in diabetes, as well as an increase in ACE2, ACE, and angiotensinogen." (PMID 32581799, 2020). "It has been reported that urinary AGT is a useful marker of intrarenal RAS activity in patients with chronic kidney disease as well as in patients with diabetes." (PMID 26380312, 2015). "In our current study, we show that p300 mRNA levels increase with diabetes and this increase was correlated with an increase in mRNA levels of fibrosis inducers: EDN1, AGT, CTGF and TGF-β1, and ECM genes, e.g. COL4A1 and FN1." (PMID 24428157, 2014). "Similar to AGT, we found that EDN1 mRNA levels were also increased in diabetes, an effect that was normalized in the miR-133a/D group." (PMID 24428157, 2014). "We measured AGT and renin expression and ANG II concentration in cardiac myocytes isolated from AT1a-KO mice after one wk of diabetes." (PMID 24215514, 2013). "The expression of AGT, Ang II, 4-HNE, and HO-1 is greater in patients with diabetes than in control subjects." (PMID 24284398, 2013). "Urinary transferrin/Cr, AGT/Cr, and VEGF-A/Cr were significantly correlated with the albumin-to-creatinine ratio but not with the GFR or diabetes risk factors, such as HbA1c or disease duration." (PMID 40362266, 2025). "During diabetes, the intrarenal renin–angiotensin system (RAS) is inappropriately activated as reflected in the stimulation of intrarenal renin and prorenin synthesis, angiotensin-converting enzyme (ACE), and intratubular levels of angiotensinogen (AGT)." (PMID 38203807, 2024). "Moreover, studies have confirmed that significant alterations in AGT and MERTK are common genes that promote diabetes and AD." (PMID 39840062, 2024). "No change in angiotensinogen was induced by diabetes alone; however, administration of candesartan to diabetic rats resulted in a significant increase of angiotensinogen." (PMID 35366272, 2021). "Simultaneously, the combination of AGT with the APOB increased by more than 50% can foster to account AGT as an indicator of DF in all studied groups irrespective of the type of diabetes mellitus." (PMID 33184417, 2020). "Thus, diabetes alters renal RAS components in a similar manner in diabetic eNOS −/− and eNOS +/+ mice and the pronounced changes in renal angiotensinogen and renin mRNA were noted in db/db eNOS −/− mice." (PMID 25371905, 2014). "Compared with individuals without diabetes, urine AGT concentration is also increased in people with type 1 diabetes and normal urine albumin excretion." (PMID 24793984, 2014). "However, no direct evidence is available to demonstrate that AGT expression is enhanced in the kidneys of patients with diabetes." (PMID 24284398, 2013). "However, in the kidney of patients with diabetes, SGLT2 inhibitors locally decrease renal angiotensinogen (AGT) expression by reducing glucose levels in the early proximal tubes, leading to increase in glucose load in the distal proximal tubule, which could increase AGT production." (PMID 33256676, 2020). "In conclusion, using carefully characterized assays, we find that in people with type 1 diabetes who have DKD, urine concentration of AGT, MMP‐7, and gremlin‐1 are markedly higher than in individuals with new onset of diabetes or those with longstanding diabetes without DKD." (PMID 24793984, 2014).